PRKG2 (protein kinase cGMP-dependent 2)
Description:
Crucial regulator of intestinal secretion and bone growth. Phosphorylates and activates CFTR on the plasma membrane. Plays a key role in intestinal secretion by regulating cGMP-dependent translocation of CFTR in jejunum. Acts downstream of NMDAR to activate the plasma membrane accumulation of GRIA1/GLUR1 in synapse and increase synaptic plasticity. Phosphorylates GRIA1/GLUR1 at Ser-863 (By similarity). Acts as a regulator of gene expression and activator of the extracellular signal-regulated kinases MAPK3/ERK1 and MAPK1/ERK2 in mechanically stimulated osteoblasts. Under fluid shear stress, mediates ERK activation and subsequent induction of FOS, FOSL1/FRA1, FOSL2/FRA2 and FOSB that play a key role in the osteoblast anabolic response to mechanical stimulation (By similarity).
Synonyms: cGK2; cGKII; PRKGR2; PKG2; AMD4; SMDP
Tractability: Small molecule: a structure with a bound ligand is known; a high-quality ligand is known; it belongs to a druggable protein family. Antibody: UniProt places it where antibodies can reach, with high confidence; its Gene Ontology location is reachable by antibodies, with medium confidence. PROTAC: ubiquitination databases record sites on it; a small molecule that binds it is known.
Target class: Kinase; AGC protein kinase group; Enzyme; AGC protein kinase PKG family; Protein Kinase
Gene: Protein-coding gene on chromosome 4 (81,086,874 to 81,217,970, reverse strand). Ensembl gene ENSG00000138669.
Subcellular location: Apical cell membrane
Pathways (Reactome):
Signal Transduction: Ca2+ pathway; RAS processing
Disease: Maturation of DENV proteins
Hemostasis: cGMP effects
Metabolism: Tetrahydrobiopterin (BH4) synthesis, recycling, salvage and regulation
Gene Ontology:
Molecular function: cGMP-dependent protein kinase activity; mitogen-activated protein kinase binding; protein serine kinase activity; ATP binding; identical protein binding; protein kinase activity; protein serine/threonine kinase activity
Biological process: intracellular signal transduction; signal transduction; tetrahydrobiopterin metabolic process; positive regulation of chondrocyte differentiation; positive regulation of protein localization; protein localization to plasma membrane
Cellular component: cytosol; apical plasma membrane; nuclear membrane
Genetic constraint (gnomAD): Loss-of-function variants: 22 observed, 65.6 expected, observed/expected ratio (o/e) 0.34, 90% interval 0.24 to 0.48. The upper end of that interval is the gene's LOEUF score, 0.48, which puts it in group 2 of 6, group 1 being the genes least tolerant of losing a copy. Missense variants: 531 observed, 774.76 expected, observed/expected ratio (o/e) 0.69, 90% interval 0.64 to 0.74. Synonymous variants: 284 observed, 286.79 expected, observed/expected ratio (o/e) 0.99, 90% interval 0.9 to 1.09.
Homologues: Orthologues: chimpanzee PRKG2 (100% identical), macaque PRKG2 (99% identical), rabbit PRKG2 (98% identical), pig PRKG2 (98% identical), mouse Prkg2 (97% identical), dog PRKG2 (97% identical), rat Prkg2 (96% identical), guinea pig PRKG2 (96% identical), tropical clawed frog prkg2 (71% identical), zebrafish prkg2 (69% identical), Drosophila melanogaster CG12069 (17% identical), Drosophila melanogaster Pka-C2 (16% identical). Paralogues in human: PRKG1 (46% identical), PRKACA (21% identical), PRKACB (20% identical), PRKX (20% identical), PRKACG (19% identical).
Diseases named in the same sentence as PRKG2 in open-access papers:
PRKG2 is named in the same sentence as 52 diseases in open-access papers, as found by Europe PMC text mining. Sharing a sentence is not in itself a finding about the gene and the disease. The quoted sentences say what the papers report.
dwarfism (6 papers, 2009 to 2025). "Previous studies have shown that the protein kinase cGMP-dependent 2 (PRKG2) gene is associated with dwarfism in humans, dogo Argentines, and Angus cattle, as well as with height and osteoblastogenesis in humans." (PMID 36600198, 2023). "Studies have demonstrated that the PRKG2 gene was associated with dwarfism in American Angus cattle, dogo Argentines, and humans." (PMID 36600198, 2023). "Together with the comparative data from other species, our data strongly suggest PRKG2:c.1634+1G>T to be a candidate causative variant for the observed dwarfism phenotype in Dogo Argentino dogs." (PMID 34680883, 2021). "In summary, we describe a new form of inherited disproportionate dwarfism in Dogo Argentino dogs and provide the PRKG2:c.1634+1G>T splice donor variant as a candidate causative variant." (PMID 34680883, 2021). "PRKG2 loss-of-function variants were previously reported to cause disproportionate dwarfism in humans, cattle, mice, and rats." (PMID 34680883, 2021). "Furthermore, naturally occurring mutations in PRKG2 have been shown to cause dwarfism in rats (Komeda miniature rat Ishikawa, KMI) and American Angus cattle." (PMID 41296694, 2025). "Furthermore, three recent cases of dwarfism in Dalmatians were found to be homozygous for the identified PRKG2 nonsense variant." (PMID 41296694, 2025). "Loss of PRKG2 function in rodent and bovine models results in dwarfism." (PMID 25924610, 2015). "In the dog breed Dogo Argentino, a splice donor variant in PRKG2 (PRKG2:XM_022413533.1, c.1634 + 1G > T, OMIA:001485–9615), has been implicated in a disproportionate form of dwarfism." (PMID 41296694, 2025). "A splice site variant in PRKG2 was identified in the breed Dogo Argentino and a partial deletion of the SLC13A1 have been found in Miniature Poodles with a severe form of dwarfism." (PMID 41296694, 2025).
acromesomelic dysplasia (4 papers, 2022 to 2025). A group of extremely rare, inherited, progressive skeletal conditions that result in a particular form of short stature, called short-limb dwarfism. "The present case expands the known phenotypic spectrum of PRKG2-related skeletal dysplasias, a group for which only a limited number of variants have been described in patients with an acromesomelic dysplasia phenotype." (PMID 41574272, 2025). "Genetic variants in PRKG2 have previously been implicated in human acromesomelic dysplasia, a disorder affecting limb growth in young children." (PMID 41296694, 2025). "This PRKG2-associated form shares many clinical and radiological features with Acromesomelic dysplasia, type Maroteaux." (PMID 41574272, 2025). "This is explained by the fact that the first articles linking pathogenic PRKG2 variants to acromesomelic dysplasia emerged only in 2021, while our patient’s panel analysis was conducted in 2022, prior to the gene’s inclusion." (PMID 41574272, 2025). "These variants cause PRKG2‐related acromesomelic dysplasia (acromesomelic dysplasia 4, AMD4, MIM 619636) and PRKG2‐related spondylometaphyseal dysplasia (Pagnamenta type (SMDP, MIM 619638)." (PMID 41296694, 2025). "This is mechanistically supported, as Acromesomelic dysplasia, Maroteaux type is caused by biallelic variants in the gene encoding NPR-B, the main receptor for C-type Natriuretic Peptide (CNP), which acts upstream of cGKII (encoded by PRKG2)." (PMID 41574272, 2025).
breast carcinoma (3 papers, 2020 to 2024). "In addition, it has been reported that PRKG2 inhibits EGF-induced MAPK/c-Jun N-terminal kinase (JNK) signal transduction in human breast cancer cells and also inhibits the activation of EGFR and HER2 in gastric cancer cells." (PMID 36338974, 2022).
colon cancer (2 papers, 2017 to 2018). "Prkg2 knockout mice demonstrated crypt hyperplasia in the colon, and in the same study, ectopic PKG2 was found to reduce colony formation and proliferation in colon cancer cells." (PMID 28170448, 2017).
gout (2 papers, 2016 to 2018). A condition characterized by painful swelling of the joints, which is caused by deposition of urate crystals. "Genetic reports of the association between the PRKG2 gene and gout were inconsistent." (PMID 30123371, 2018).
Intellectual disability (2 papers, 2015 to 2023). "The PRKG2 (cGMP-dependent protein kinase) and RASGEF1B (RasGEF domain family member 1B) genes have been identified as positional candidate genes for growth restriction, aggression, self-injurious behaviours, and mental retardation in affected German Shepherd dogs." (PMID 37048405, 2023).
mast cell hyperplasia (2 papers, 2016 to 2021). "Further studies may be of benefit to determine if PRKG2/PDGFRB fusion is harbored by mast cells, which would suggest that the cases thus far described may represent a distinct clonal disorder, rather than a systemic mastocytosis with a second non-mast cell hematologic disorder." (PMID 27648315, 2016).
myeloid neoplasm (2 papers, 2016 to 2021). Proliferation of myeloid cells originating from a primitive stem cell. "Here we report a case of systemic mastocytosis related myeloid neoplasms with basophilia and PRKG2–PDGFRB fusion gene." (PMID 33663081, 2021). "We present the case of a 26-year-old woman with microcytic anemia, basophilia, thrombocytosis, and massive splenomegaly, who was found to have systemic mastocytosis and associated clonal hematological non-mast cell lineage disease (SM-AHNMD), with myeloid neoplasm with PRKG2/PDGFRB rearrangement." (PMID 27648315, 2016).
osteosarcoma (2 papers, 2009 to 2015). A usually aggressive malignant bone-forming mesenchymal neoplasm, predominantly affecting adolescents and young adults. "Interestingly, PRKG2 is located underneath a quantitative trait locus on mouse chromosome 5 for alpha-radiation induced osteosarcoma." (PMID 25924610, 2015).
spondylometaphyseal dysplasia (2 papers, 2022 to 2025). Spondylometaphyseal dysplasias are a heterogeneous group of disorders associated with walking and growth disturbances that become evident during the second year of life. "In family 1, WGS and subsequent Sanger sequencing uncovered a homozygous pathogenic PRKG2 variant, NM_006259.3:c.2282dup (p.Asp761Glufs*34) in three brothers referred with spondylometaphyseal dysplasia." (PMID 34782440, 2022).
achondroplasia (1 paper, 2015). Achondroplasia is the most common form of chondrodysplasia, characterized by rhizomelia, exaggerated lumbar lordosis, brachydactyly, and macrocephaly with frontal bossing and midface hypoplasia. "Identification of differentially enriched pathways due to loss of PRKG2 function may be useful in suggesting potential treatments for achondroplasia and other bone diseases." (PMID 25924610, 2015). "Various mouse crosses have demonstrated that transgenic modulation of CNP can rescue mice from achondroplasia caused by disruption of fibroblast growth factor receptor 3 (FGFR3), mitogen-activated protein kinase (MAPK), or PRKG2 signaling." (PMID 25924610, 2015).
achromatopsia (1 paper, 2020). Achromatopsia (ACHM) is a rare autosomal recessive retinal disorder characterized by color blindness, nystagmus, photophobia, and severely reduced visual acuity due to the absence or impairment of cone function. "Taken together, this study establishes Prkg2 as a novel therapeutic target for neuroprotection of degenerating cone photoreceptors in achromatopsia, although the therapeutic applicability of Prkg2 inhibition needs to be further validated." (PMID 33374621, 2020). "In conclusion, we identified Prkg2 as a novel key mediator of cone photoreceptor degeneration in achromatopsia." (PMID 33374621, 2020). "Based on the presented results it is tempting to speculate that a neuroprotective therapy by Prkg2 inhibition has the potential to delay degeneration of cones and to widen the window of opportunity for gene therapy in achromatopsia." (PMID 33374621, 2020).
colonic diseases (1 paper, 2017). "Several downregulated genes including Mal, Prkg2, Amn, Tmigd1, 9030624O13Rik, and Akr1b7 are known to be associated with colonic diseases." (PMID 28170448, 2017).
depression (1 paper, 2021). "In the restrained group, genes involved in long-term depression (Plcb4, Gucy1a3, Prkg2, Ppp1r17, Grid2, and Crhr1) were downregulated compared to the control group." (PMID 34276303, 2021).
hepatoma (1 paper, 2021). "The transfection of human hepatoma cells with the mutant bovine allele reduced the ability of PRKG2 to inhibit SOX9-mediated downregulation of the collagen type II expression." (PMID 34680883, 2021).
lung carcinoma (1 paper, 2024). "Thirdly, although there is a suggested correlation between PRKG2 expression levels and the immune microenvironment of lung cancer, further investigation using immunohistochemical scoring is required due to limited data." (PMID 39744538, 2024). "PRKG2 was overexpressed in A549 cells to study its impact on lung cancer cell proliferation and invasion in vitro." (PMID 39744538, 2024). "In vitro experiments confirmed elevated PRKG2 expression inhibits the proliferation and invasion of lung cancer cells." (PMID 39744538, 2024). "The PRKG2 expression levels in tissues from SSc and lung cancer patients were significantly lower than those of normal individuals, as evidenced by the GSE95065 and GSE136043 datasets." (PMID 39744538, 2024). "In our study, the expression level of PRKG2 demonstrated a significant positive correlation with macrophages and dendritic cells within the immune microenvironment of lung cancer." (PMID 39744538, 2024). "As a core gene common to both diseases, PRKG2 exerts a significant influence on the proliferation and migration of lung cancer." (PMID 39744538, 2024). "In the lung cancer group, PRKG2 exhibited significant positive correlation with NFE2L2, SLC40A1, TFRC, and significant negative correlation with CHAC1 and HSPB1." (PMID 39744538, 2024). "PRKG2 is one of the genes shared by SSc and lung cancer, affecting the proliferation and invasion of lung cancer cells." (PMID 39744538, 2024). "These correlations suggest that PRKG2 may play a role in inhibiting lung cancer development through the modulation of these immune cells." (PMID 39744538, 2024). "Building on this hypothesis, we overexpressed PRKG2 in lung cancer cell lines in vitro and found that it significantly inhibited cell growth, invasion, and migration, aligning with previous research." (PMID 39744538, 2024). "In conclusion, we propose PRKG2 as a core shared gene between SSc and lung cancer." (PMID 39744538, 2024). "Secondly, while we examined the effects of PRKG2 on lung cancer cells and the expression of PRKG2 in fibroblasts from lung tissues of SSc-ILD patients, we did not evaluate the effects of PRKG2 in SSc animal models, an aspect we plan to address in future research." (PMID 39744538, 2024). "This suggests that PRKG2 may exert a sustained inhibitory effect on the onset and progression of lung cancer." (PMID 39744538, 2024). "Consequently, low expression of PRKG2 facilitates the growth and migration of lung cancer." (PMID 39744538, 2024). "By intersecting these top DEGs, we recognized seven genes potentially involved in the pathogenesis of both SSc and lung cancer: SCN7A, AGTR1, WIF1, PRKG2, LTF, AQP4, and COL10A1." (PMID 39744538, 2024). "We categorized all lung cancer patients from the GEPIA2 database into low and high PRKG2 expression groups based on the median expression value of PRKG2." (PMID 39744538, 2024). "Furthermore, analysis of independent validation datasets confirmed that PRKG2 is the most effective gene for distinguishing SSc and LUAD from the normal population, suggesting that PRKG2 is a core gene shared between SSc and lung cancer." (PMID 39744538, 2024).
lymph node metastasis (1 paper, 2024). "The PRKG2 expression levels of LUAD patients with different clinical stages and lymph node metastasis states were consistently lower than those observed in normal individuals." (PMID 39744538, 2024). "The expression of PRKG2 in LUAD patients with different clinical stages and lymph node metastasis status was significantly lower than that in the normal population." (PMID 39744538, 2024).
cancer (10 papers, 2017 to 2024). A tumor composed of atypical neoplastic, often pleomorphic cells that invade other tissues. "Lastly, WWOX silencing-depended survival of cancer cells can be also associated with PRKG2 gene E2-induced expression." (PMID 35290621, 2022). "Further analysis on cancer cell-specific genes revealed that KPmut-Late tumors exhibit elevated expression levels of several genes, including Prkg2, Hmga2, Wincr1, Cdkn2a, Tnnt2, Aqp5, and Sprr1." (PMID 37998349, 2023). "We therefore continued with a 2D proliferation analysis for synergismin five KRAS mutant and dependent cancer cell lineswith diverse levels of PDE6D and PRKG2 dependencies." (PMID 38758695, 2024). "PRKG2 inhibits the migration, invasion, and proliferation of cancer cells and activates CREB, which modulates anti-apoptotic genes, such as BCL2, which are overexpressed in the resistant group, thereby contributing to the survival of cancer cells in the resistant group." (PMID 36338974, 2022).
tumor (4 papers, 2012 to 2022). "Twenty-three of the genes associated with tumor-specific response had a false discovery rate <20%, including IGF, whereas only one gene associated with clinical response, PRKG2, had FDR <20%." (PMID 35892846, 2022).
infection (2 papers, 2018 to 2023). The state of being infected such as from the introduction of a foreign agent such as serum, vaccine, antigenic substance or organism. "In addition, the PI3K-Akt signaling pathway-related genes were expressed at lower levels in SFTSV infection 24 and 48 h, for example, GP1BA, PIK3CA, PIK3CB, AKT3, PRKG1, and PRKG2." (PMID 37211158, 2023).
neurodegenerative disease (1 paper, 2020). A disorder of the central nervous system characterized by gradual and progressive loss of neural tissue and neurologic function. "Our findings open up a new avenue to further investigate the role of PRKG2 in MS and other neurodegenerative diseases." (PMID 32270922, 2020).
PRKG2 also shares sentences with these, for which no sentence is quoted: gastric cancer (3 papers); glioma (2); melanoma (2); multiple sclerosis (2); Obesity (2); skeletal dysplasia (2); systemic mastocytosis (2); Anxiety (1); Atrophy (1); breast tumor (1); chondrodysplasia (1); developmental delay (1); diabetes (1); diarrheal disease (1); Ewing sarcoma (1); HCMV infection (1); head and neck squamous cell carcinoma (1); hematologic neoplasm (1); Huntington disease (1); hyperthyroidism (1); keloid (1); metabolic disease (1); microcytic anemia (1); neuroblastoma (1); non-small cell lung carcinoma (1); osteoporosis (1); pulmonary diseases (1); pulmonary fibrosis (1); Splenomegaly (1); Thrombocytosis (1).
A further 1 disease shares a sentence with PRKG2 in 1 paper.